S100B (S100 calcium binding protein B)
Diseases named in the same sentence as S100B in open-access papers (continued):
Sharing a sentence is not in itself a finding about the gene and the disease.
irritable bowel syndrome (2 papers, 2025). Irritable bowel syndrome (IBS) is a chronic functional condition of the lower gastrointestinal (GI) tract characterized by abdominal pain or discomfort and disordered bowel habit (diarrhea, constipation, or fluctuation between the two). "And compared to control rats and enteric glial cells, the expression levels of GFAP, S100B, SP, CGRP, TRPV1, TNF, IL-1β, and IL-6, were significantly higher in the colonic tissues of irritable bowel syndrome (IBS) rats and lipopolysaccharide (LPS)-treated EGCs." (PMID 40225339, 2025).
keloid (2 papers, 2022 to 2024). An irregularly shaped, elevated mark on the skin caused by deposits of excessive amounts of collagen during wound healing. "In contrast, some keloids contained Schwann cells coexpressing fibroblast markers and S100B (double positive, yellow dots in keloids)." (PMID 36333467, 2022).
kidney damage (2 papers, 2020 to 2024). "Any attempt to draw conclusions from the results of S100B measurement in the nephropathy patient group should therefore be first analyzed considering the timing of dialysis relative to blood collection." (PMID 39519343, 2024).
Lyme neuroborreliosis (2 papers, 2022 to 2024). "In VZV CNS infections, S-100B has been reported to be decreased in the CSF while normal CSF levels of S-100B has been observed in other CNS infections such as neuroborreliosis and in tick-borne encephalitis." (PMID 38756101, 2024).
melancholic depression (2 papers, 2015 to 2023). "This study examined whether circulating S100B levels in the serum of patients with melancholic depression are associated with outcome after antidepressant treatment." (PMID 26364276, 2015).
meningoencephalitis (2 papers, 2018 to 2021). Inflammation of the meninges and brain, generally secondary to an infectious cause. "Other important observation is that NSE and S100B concentrations were increased in sample 2 in meningoencephalitis, which suggests that despite clinical recovery of the majority of patients, the neurons were still being damaged." (PMID 30468006, 2018).
mucositis (2 papers, 2017 to 2019). Mucositis is inflammation and damage of the mucous membranes lining the mouth and other parts of the gastrointestinal (GI) tract. "Here, we found that 5-FU increases RAGE and NFκB p65 protein expression within the jejunum, primarily by the intestinal epithelium and enteric neurons, suggesting that S100B may contribute to the intestinal injury during mucositis and to neuronal loss." (PMID 30679569, 2019). "We also demonstrated that 5-FU upregulates S100B protein expression in GFAP-positive cells during mucositis, suggesting that EGCs are an important source of S100B on this model." (PMID 30679569, 2019). "We also showed that S100B is produced by EGCs and may be involved in enteric neuron death and reactive gliosis during mucositis as well as in the histological alterations, animal weight loss, inflammatory response and oxidative stress through a RAGE/NFκB-dependent mechanism." (PMID 30679569, 2019).
muscular dystrophy (2 papers, 2017 to 2021). Muscular dystrophy (MD) refers to a group of more than 30 genetic diseases characterized by progressive weakness and degeneration of the skeletal muscles that control movement. "Moreover, a recent study has proved that S100B is associated with the reparative process in acute muscle injury and muscular dystrophy by regulating the M1/M2 macrophage levels." (PMID 34250093, 2021). "Next, we examined S100B in muscles of mdx mice, an animal model of muscular dystrophy, characterized by a high inflammatory component." (PMID 28970581, 2017). "Thus, levels of S100B differentially affect skeletal muscle repair upon acute injury and in the context of muscular dystrophy, and S100B might be regarded as a potential molecular target in DMD." (PMID 28970581, 2017).
myositis (2 papers, 2013 to 2020). "Nivolumab monotherapy was started and myositis with an increase of myoglobulin was observed at day 98 with a parallel increase of IL6 as well as of S100B." (PMID 32188047, 2020).
neuroma (2 papers, 2019 to 2025). A tumor that grows from a nerve or is composed of nerve cells and nerve fibers. "To explore the factors associated with the longer time to improve taste function in later cases than early cases, we analyzed 30 samples of traumatic neuromas fixed by formalin in the immunohistochemistry using anti-S100β antibody to recognize Schwann cells." (PMID 31921714, 2019).
pancreatic adenocarcinoma (2 papers, 2020 to 2021). "Furthermore, by analyzing the publicly accessible datasets for patients with pancreatic adenocarcinoma (PAAD), we found that the gene expression of three typical SC markers, GFAP, S100B, and SRY-box transcription factor 10 (SOX10), was significantly associated with that of several EMT markers." (PMID 32308766, 2020).
pancreatic cancer (2 papers, 2019 to 2021). "Regarding the S100 family, different members, including S100A2, S100A8, and S100B, have been correlated with chemotherapy response in both breast and pancreatic cancer patients." (PMID 31779212, 2019).
paraplegia (2 papers, 2019 to 2025). Complete paralysis of the lower half of the body including both legs, often caused by damage to the spinal cord. "Serum S100B levels were significantly higher in patients with paraplegia compared to those with paraparesis at initially measured intervals of up to two weeks, reflecting the greater severity of neurological damage in complete injuries." (PMID 40125181, 2025). "On further analyzing the variation of serum S100 levels in cases, the serum S100B level in the case of paraplegia was higher than in the case of paraparesis across baseline, two weeks, and six weeks." (PMID 40125181, 2025). "The rate of decline in S100B levels was steeper in paraparesis patients than in paraplegia cases." (PMID 40125181, 2025). "Among those 8 patients operated on, onesuffered from delayed-onset postoperative paraplegia, and it was noted that CSFS-100β continued to rise from skin closure and 24 hours postoperatively,unlike the other 7 patients in whom S-100β decreased following skinclosure." (PMID 31454201, 2019).
pneumonia (2 papers, 2023 to 2025). An acute, acute and chronic, or chronic inflammation focally or diffusely affecting the lung parenchyma, caused by an infection in one or both of the lungs (by bacteria, viruses, fungi, or mycoplasma.). "In contrast, although S100B shows a strong association with pneumonia and disease progression, its role in guiding early intervention strategies remains insufficiently defined." (PMID 41585373, 2025). "In contrast, the low heterogeneity (I2 < 30%) across studies examining IL-6 and S100B levels in patients with pneumonia indicates more uniform findings." (PMID 41585373, 2025).
prediabetes (2 papers, 2025). "The elevated level of S100B in the PD group can be attributed to the fact that individuals with prediabetes often experience intermediate insulin resistance, chronic inflammation and metabolic dysfunction." (PMID 41296388, 2025). "The incremental rise in S100B levels from the NPD to PD to T2D group reflects the increasing severity of brain injury, with prediabetes serving as an intermediary stage." (PMID 41296388, 2025).
relapsing remitting MS (2 papers, 2012 to 2021). "It is reported that S100β was significantly elevated in patients' cortexes with relapsing remitting MS." (PMID 23493953, 2012).
sarcopenia (2 papers, 2022 to 2023). Progressive decline in muscle mass due to aging which results in decreased functional capacity of muscles. "The secretion or release of S100B relates to cell metabolism regulation, in processes involved in neurite extension, cancer, muscle regeneration, and restricted energy in sarcopenia." (PMID 35625541, 2022).
schwannomatosis (2 papers, 2015 to 2023). The least frequent form of the rare genetic disorder neurofibromatosis. "The schwannomatosis cells also expressed the Schwann cell markers, p75NTR, S100B, and NGF after multiple passages." (PMID 26657314, 2015). "The schwannomatosis cell lines were stained with S100B antibodies to confirm Schwann cell identity." (PMID 26657314, 2015). "Primary Human Schwann cells, and schwannomatosis cell lines (Hp-SWN-14F and Hnp-SWN-14O) all positively stained for S100B after multiple passages and freeze-thaw cycles." (PMID 26657314, 2015).
spinal cord injury (2 papers, 2019 to 2021). Penetrating and non-penetrating injuries to the spinal cord resulting from traumatic external forces (e.g., WOUNDS, GUNSHOT; WHIPLASH INJURIES; etc.). "There is controversy regarding the value of serum or cerebrospinal fluid (CSF) levels of S100 calcium-binding protein B (S-100B) in spinal cord injury (SCI)." (PMID 31432029, 2019).
spinal cord ischemia (2 papers, 2017 to 2018). Reduced blood flow to the spinal cord which is supplied by the anterior spinal artery and the paired posterior spinal arteries. "Also, S100b increases intrathecally after spinal cord ischemia, but this takes longer, up to 6 h." (PMID 30367354, 2018). "While our results suggest the possibility of mild spinal cord ischemia (based on elevated S-100-B levels), this did not result in increasing antioxidant capacity in the spinal cord (based on unchanged Trolox levels)." (PMID 28740858, 2017).
TB meningitis (2 papers, 2023 to 2024). "When comparing the aseptic, bacterial, and tuberculous meningitis groups, ALOX5 and S100B showed the highest VIP scores." (PMID 38115295, 2023).
temporal lobe epilepsy (2 papers, 2020 to 2023). A localization-related (focal) form of epilepsy characterized by recurrent seizures that arise from foci within the temporal lobe, most commonly from its mesial aspect. "Increased expression of S100B was shown in patients with temporal lobe epilepsy (TLE)." (PMID 36766708, 2023).
Vertigo (2 papers, 2020). An abnormal sensation of spinning while the body is actually stationary. "Considering the high sensitivity and specificity at the cut-off point of 19.2 ng/ml, it seems that NSE is more valuable than S100B in differentiating peripheral and central causes of vertigo." (PMID 32021984, 2020). "In conclusion, this study suggests that the serum NSE and S100β concentrations could be useful markers for distinguishing vertigo of central causes, such as a posterior circulation cerebral infarct or VBI, from peripheral causes and controls in the emergency setting." (PMID 32266274, 2020). "S100B had the area under the ROC curve of 90.3 (95% CI: 80.7 – 99.8) for differentiating the causes of acute vertigo, and at the cut-off point of above 119.68 pg/l, had sensitivity of 90.00% and specificity of 92.00%, in detecting cases with abnormal MRI findings (central cause of vertigo)." (PMID 32021984, 2020). "The present study aimed to examine the potential screening values of S100B and NSE in differentiating true vertigo cases with central causes in the ED." (PMID 32021984, 2020). "Another study found that serum S100β levels were associated with the presence of central causes of vertigo on brain MRI, although the levels were not sufficiently sensitive to exclude candidates for brain MRI." (PMID 32266274, 2020). "In addition, serum S100β levels were significantly higher in posterior circulation stroke patients than in nonvascular vertigo patients." (PMID 32266274, 2020).
Zinc deficiency (2 papers, 2017 to 2021). A deficiency of the essential metal Zinc; an essential cofactor for many enzymes. "Abnormal accumulation of S100B under physiological zinc levels may thus result in local zinc deficiency." (PMID 29386995, 2017). "Thus, we investigated whether crosstalk between high S100B levels and zinc deficiency exists, acting on known ASD-associated pathways at excitatory synapses, thereby linking hypozincemia, inflammation, and known genetic factors in a single synaptic pathomechanism of ASD." (PMID 34741005, 2021).
Acute hepatic failure (1 paper, 2023). "This study reveals that acute hepatic failure induces astrocyte damage, as seen by elevated S100B serum levels, and that this astrocyte damage can be mitigated with BAL therapy." (PMID 37760829, 2023). "They reported that acute hepatic failure led to increased S100B serum protein levels and that S100B levels were particularly elevated in animals that died from induction of acute hepatic failure." (PMID 37760829, 2023). "Kanai and colleagues induced acute hepatic failure in male mini-pigs by administration of 0.05 mg/kg alpha-amanitin and 1 ug/kg lipopolysaccharide (LPS) in the splenic vein and investigated the effect of this injury on blood serum S100B levels with ELISA several hours after injury." (PMID 37760829, 2023).
adenoma (1 paper, 2025). A neoplasm arising from the epithelium. "Furthermore, S100B staining was found in normal mucosa, adenoma, and carcinoma tissue of all patients, confirming the presence of enteric glial cells." (PMID 40580485, 2025). "Since we observed S100B-expressing enteric glia in normal mucosa, adenoma and carcinoma tissue, we hypothesize that these cells represent mucosal enteric glia that upregulate GFAP, rather than cells that migrated centripetally from outer plexus layers into the tumor." (PMID 40580485, 2025). "Healthy, adenoma, and tumor tissues from CRC patients were immunohistochemically stained for the glial markers S100B and glial fibrillary acidic protein (GFAP)." (PMID 40580485, 2025). "To investigate the presence and marker expression of enteric glia, we evaluated S100B and GFAP expression in human samples of adjacent normal mucosa, adenoma, and carcinoma tissue from the same CRC patient." (PMID 40580485, 2025). "Of note, we showed that normal mucosa and adenoma tissue harbor S100B-positive enteric glia that are not immunoreactive for GFAP." (PMID 40580485, 2025).
adenomyosis (1 paper, 2022). The growth of endometrial tissue inside the muscular wall of the uterine corpus. "Within mice with EMID-induced adenomyosis, the density of S100β+ SCs reduced progressively with time (p = 1.9 × 10−5), but treatment with SP600125 or U0126 resulted in a significant increase in the density of S100β+ SCs in the EMI (p = 2.8 × 10−8 and p = 1.9 × 10−5, respectively, R2 = 0.76)." (PMID 35740240, 2022).
Adrenal insufficiency (1 paper, 2014). Insufficient production of steroid hormones (primarily cortisol) by the adrenal glands. "Unlike S100B, cortisol was not solely a biomarker of brain dysfunction but was related with underlying life-threatening homeostasis disturbance of the host: abnormal HPA stress hormones response, glucose intolerance, immunodepression, and adrenal insufficiency." (PMID 24883321, 2014).
adrenal pheochromocytomas (1 paper, 2021). "In the adrenal pheochromocytomas, a third cell type with the positive expression of S100B was identified, called ‘sustentacular’ cells." (PMID 34905486, 2021).
Alexander disease (1 paper, 2007). Alexander disease (AxD) is a rare neurodegenerative disorder of the astrocytes comprised of two clinical forms: AxD Type I and Type II manifesting with various degrees of macrocephaly, spasticity, ataxia and seizures and leading to psychomotor regression and death. "Other predictions include involvement of MCM2 and MCM3 in hypolactasia, S100B in Alexander disease, and CFHL1 in chronic hypocomplementemic nephropathy." (PMID 18042286, 2007).
angina pectoris (1 paper, 2020). The symptom of paroxysmal pain consequent to MYOCARDIAL ISCHEMIA usually of distinctive character, location and radiation. "AMI patients (n = 125) had significantly higher systemic S100B levels, as compared to those in stable angina pectoris (n = 122) and controls subjects (n = 120) [median (IQR):302.16 (606.50–103.18) vs. 159.50 (315.69–45.38) vs. 119.45 (300.23–20.41)]." (PMID 33796567, 2020). "In the present study, we found that plasma S100B levels were significantly higher in AMI patients than in the control subjects and stable angina pectoris patients." (PMID 33796567, 2020).
Aortic dissection (1 paper, 2025). Aortic dissection refers to a tear in the intimal layer of the aorta causing a separation between the intima and the medial layers of the aorta. "Other novel inflammatory markers were also examined to determine their prognostic value in patients with Type A aortic dissection, such as S100A8/A9, pentraxin 3, chitinase 3-like 1, and S100B." (PMID 39910669, 2025).
arteriosclerosis (1 paper, 2021). A vascular disorder characterized by thickening and hardening of the walls of the arteries. "We conclude that hedgehog-responsive S100β vSCs contribute to lesion formation and support targeting hedgehog signalling to treat subclinical arteriosclerosis." (PMID 33649337, 2021).
benign meningioma (1 paper, 2023). A grade I, slowly growing meningioma. "Except for 1 study with 63 samples reporting a higher frequency of S100B expression in benign meningiomas, there is little information regarding the prognostic role of S100 in meningiomas." (PMID 35838837, 2023).
bowel obstruction (1 paper, 2012). "The subsequent dramatic elevation of both KLK6 and S100B proteins after 170 hours, may be associated with the suffered bowel obstruction." (PMID 23049835, 2012).
brain arteriovenous malformations (1 paper, 2020). "Secondary elevation of S100B protein serum levels is associated with secondary infarction in ruptured brain arteriovenous malformations." (PMID 33172087, 2020). "Early S100B protein serum elevation is associated with poor prognosis in patients with ruptured brain arteriovenous malformations (BAVM)." (PMID 33172087, 2020).
Cachexia (1 paper, 2020). Severe weight loss, wasting of muscle, loss of appetite, and general debility related to a chronic disease. "The combination of elevated serum S100B levels and RAGE overexpression in muscles, as seen in tumour‐bearing mice and cytokine‐induced experimental cachexia, switches the effect of the S100B‐RAGE pair from trophic to atrophying." (PMID 32159297, 2020). "Collectively, these results suggested that overexpression and hyper‐stimulation of RAGE induced by high S100B might trigger muscle atrophy via a p38 MAPK/myogenin axis and STAT3‐dependent MyoD degradation, possibly amplifying the activity of cachexia‐inducing cytokines." (PMID 32159297, 2020).
carbohydrate metabolism disorders (1 paper, 2020). "The S100B protein seem to be interesting in this respect as it may be a potential candidate, especially important in early diagnostics of these diseases, given that it plays a role in both carbohydrate metabolism disorders and neurodegenerative processes." (PMID 32326589, 2020).
cardioembolic stroke (1 paper, 2019). "Data mining analysis showed that plasma levels of NT-proBNP ≥ 0.5 ng/mL and S100β ≥ 0.1 ng/mL are associated with cardioembolic stroke, with a sensitivity and a specificity higher than 85%." (PMID 31163612, 2019). "Recent studies have shown that elevated plasma NT-proBNP and S100β levels are predictive of cardioembolic stroke." (PMID 31163612, 2019).
carotid atherosclerosis (1 paper, 2022). A thickening and loss of elasticity of the walls of carotid arteries that occur with formation of atherosclerotic plaques. "Surprisingly, the carotid artery specimen revealed a decreased expression of HMGB1 and S100B with a concomitant increase in the pro-inflammatory cytokines IL-17, IL-18 and IL-1β suggesting the priming role of DAMPs in initiating carotid atherosclerosis." (PMID 35531433, 2022).
cerebral aneurysm (1 paper, 2023). "Contrasting to presented studies, our results indicated that both hNSE and S100B would not work as potential biomarkers of brain damage following uncomplicated cerebral aneurysm embolization, probably due to lack of sufficient neuronal injury." (PMID 37759909, 2023).
chronic myeloid leukemia (1 paper, 2022). "It inhibits the interactions between RAGE and its ligands, including Aβ1-42, HMGB1 (high mobility group box 1), S100B, and CML (chronic myeloid leukemia)." (PMID 36389082, 2022).